LINC01012 (long independently transcribed non-coding RNA 1012)
Gene: Long non-coding RNA gene on chromosome 6 (27,687,617 to 27,715,556, forward strand). Ensembl gene ENSG00000281706.
Gene Ontology:
Molecular function: triplet codon-amino acid adaptor activity
Biological process: translation
Diseases named in the same sentence as LINC01012 in open-access papers:
LINC01012 is named in the same sentence as 1 disease in open-access papers, as found by Europe PMC text mining. Sharing a sentence is not in itself a finding about the gene and the disease. The quoted sentences say what the papers report.
gastric cancer (1 paper, 2023). A primary or metastatic malignant neoplasm involving the stomach. "LINC01012 expression is elevated in gastric cancer tissues, and the proliferation of gastric cancer cells decreased following transfection with siRNA interfering with LINC01012." (PMID 37846311, 2023).